GRB10 (growth factor receptor bound protein 10)
Diseases named in the same sentence as GRB10 in open-access papers (continued):
Sharing a sentence is not in itself a finding about the gene and the disease.
Sepsis (2 papers, 2023 to 2025). Sepsis is defined as life-threatening organ dysfunction caused by a dysregulated host response to infection. "In conclusion, this integrated approach provides profound insights into the molecular mechanisms underlying sepsis, pinpointing BMX, GRB10, and GADD45A as pivotal biomarkers and therapeutic targets." (PMID 40230692, 2025). "Collectively, these features position BMX, GRB10, and GADD45A as potential key contributors to the interplay of hyperinflammation, immunosuppression, and oxidative stress that underlies sepsis progression." (PMID 40230692, 2025). "These efforts aim to incorporate BMX, GRB10, and GADD45A into diagnostic panels and personalized treatment strategies, thereby improving sepsis management and patient outcomes." (PMID 40230692, 2025). "Integration of the outputs from all five algorithms identified BMX, GRB10, and GADD45A as the core biomarkers for sepsis, reinforcing their reliability for diagnosis." (PMID 40230692, 2025). "GSVA analysis further confirmed the roles of BMX, GRB10, and GADD45A in immune dysregulation during sepsis, highlighting their involvement in immune environment alterations." (PMID 40230692, 2025). "We examined the expression of BMX, GRB10, and GADD45A in sepsis patients, observing significantly elevated expression in sepsis compared to healthy controls." (PMID 40230692, 2025). "Despite our robust findings, several limitations must be addressed to fully utilize BMX, GRB10, and GADD45A as sepsis biomarkers and therapeutic targets." (PMID 40230692, 2025). "The chord diagram highlighted BMX, GRB10, and GADD45A’s involvement in reactive oxygen species metabolism, a critical pathway in sepsis." (PMID 40230692, 2025). "In conclusion, this study leverages integrated transcriptomics and ML approaches to identify BMX, GRB10, and GADD45A as pivotal biomarkers and therapeutic targets in sepsis." (PMID 40230692, 2025). "Other biomarkers also correlate with outcome/prognosis e.g., CD177, FGF13, GRB10 and PPARG in both SIRS and sepsis." (PMID 38332914, 2023). "For instance, the BMX-miR-758-3p-AC079586.1 and GRB10-miR-15a-5p-RP11-483P21.6 axes highlight potential regulatory mechanisms through which non-coding RNAs may influence gene expression and sepsis progression." (PMID 40230692, 2025).
abortion (1 paper, 2021). the ending of pregnancy by removing a fetus or embryo before it can survive outside the uterus. "Previous studies have found an increase methylation of GRB10 in fetal samples of spontaneous abortion." (PMID 33407475, 2021).
astrocytoma (1 paper, 2015).
Autoimmunity (1 paper, 2021). The occurrence of an immune reaction against the organism's own cells or tissues. "Therefore, we hypothesize that Neanderthal introgressed alleles regulate the expression or splicing of GRB10 contributing to changes in monocytes that may lead to protection from autoimmunity." (PMID 34294692, 2021).
Beckwith-Wiedemann syndrome (1 paper, 2025). Beckwith-Wiedemann syndrome (BWS) is a genetic disorder characterized by overgrowth, tumor predisposition and congenital malformations. "More recently, a case study was published regarding a CNV deletion in chromosome 7, which involved several protein-coding genes including GRB10 and resulted in a complex phenotype that included features of Beckwith-Wiedemann syndrome, a recognized prenatal overgrowth condition." (PMID 40577202, 2025).
bladder cancers (1 paper, 2025). "The GSEA results also indicated that low expression of the MACC1, GRB10 and MARCKS genes, along with high expression of the NINJ2 gene, were associated with tumourigenesis, including breast, pancreatic and bladder cancers." (PMID 39926275, 2025).
cataract (1 paper, 2023). Partial or complete opacity of the crystalline lens of one or both eyes that decreases visual acuity and eventually results in blindness. "Even though patient #50 had a confirmatory research test of an LP variant in the GRB10 gene, yet no variants in this gene have been previously associated with cataracts in the published literature." (PMID 36980880, 2023).
chronic myelogenous leukemia (1 paper, 2016). "GRB10 interacts with oncogenic Bcr-Abl in chronic myelogenous leukemia, and with active Raf-1 to promote cell survival, and it also binds with FLT3 to enhance AML cell proliferation, which is suggestive of oncogenicity." (PMID 27977763, 2016).
COVID-19 (1 paper, 2024). A disease caused by infection with severe acute respiratory syndrome coronavirus 2. "In addition, we used multiple machine learning methods to screen for five risk genes (KLF5, NSUN7, APH1B, GRB10 and CD4), which are used to predict COVID-19 severity." (PMID 38600309, 2024).
developmental delay (1 paper, 2017). "PPIA, IGFBP-3, GCK, GRB10, and H2AFV have HI <10% and that patient’s phenotype includes global developmental delay, tall stature, macrocephaly, depressed nasal bridge, pectus excavatum, and hypospadias." (PMID 28387648, 2017).
diabetic nephropathy (1 paper, 2016). "Meanwhile, we found that catalpol treatment significantly abrogated the elevated expression of Grb10 protein in diabetic kidneys, suggesting that catalpol ameliorated renal function loss and pathological damages possibly by down-regulating Grb10 expression in diabetic nephropathy." (PMID 26986757, 2016). "Collectively, our findings support the notion that catalpol exerts its therapeutic effects on diabetic nephropathy possibly by down-regulating Grb10 expression and the subsequent activation of IGF-1/IGF-1R signaling." (PMID 26986757, 2016). "The IGF1-1R pathway is critical for cell growth and apoptosis and has been implicated in kidney diseases; however, it is still unknown whether Grb10 expression is up-regulated and plays a role in diabetic nephropathy." (PMID 26986757, 2016). "Our results suggest that elevated Grb10 expression may play an important role in the pathogenesis of diabetic nephropathy through suppressing IGF-1/IGF-1R signaling pathway, which might be a potential molecular target of catalpol for the treatment of this diabetic complication." (PMID 26986757, 2016).
Facioscapulohumeral dystrophy (1 paper, 2008). Facioscapulohumeral muscular dystrophy (FSHD) is characterized by progressive muscle weakness with focal involvement of the facial, shoulder and limb muscles. "In an independent microarray study of 10 men and 9 women with facioscapulohumeral dystrophy, women had higher expression of GRB10 (2.7-fold, P<0.001) and ACVR2B (1.7-fold, P<0.03)." (PMID 18167544, 2008).
gestational diabetes (1 paper, 2022). Carbohydrate intolerance first diagnosed during pregnancy. "Interestingly, the patients of both groups exhibited almost identical expression levels, meaning that IGF2 and GRB10 genes are maintained at similar levels in healthy and in gestational diabetes patients." (PMID 35454338, 2022).
injury (1 paper, 2025). Damage inflicted on the body as the direct or indirect result of an external force, with or without disruption of structural continuity. "circHtra1 regulates growth factor receptor-bound protein 10 (GRB10) expression by adsorbing miR-3960, which promotes neuronal apoptosis and worsens neuronal cell loss after brain injury." (PMID 41446042, 2025).
invasive breast carcinoma (1 paper, 2021). A carcinoma that infiltrates the breast parenchyma. "Similarly, studies have shown the relationship between the aberrant methylation of the GRB10 gene and invasive breast cancer." (PMID 34906185, 2021).
metastatic tumors (1 paper, 2015). "Consistent with our immunoblotting observations under ex vivo and in vivo conditions, MEGF10, KRTAP1-1, SEMA3D, MYC, and GRB10 IHC staining revealed relatively strong positivity in metastatic tumors." (PMID 26148557, 2015).
omphalocele (1 paper, 2019). Omphalocele is an embryopathy classified in the group of abdominal celosomias and is characterized by a large hernia of the abdominal wall, centered on the umbilical cord, in which the protruding viscera are protected by a sac. "Another case (patient 34) was ascertained with omphalocele, shortened humeri and mesenchymal placenta, and showed LOM of IC2, GRB10 and MEST loci." (PMID 30829192, 2019).
oncocytic thyroid carcinomas (1 paper, 2019). "In oncocytic thyroid carcinomas, ASE analysis of GRB10 and MEST showed a high degree of variability of the distribution of isoforms expressed per allele." (PMID 31093489, 2019).
overgrowth syndrome (1 paper, 2025). A group of syndromes caused by genetic birth defects that may lead to the development of malignancies. "Our patient, born large for gestational age, macrocephalic, and with tall stature, provides further evidence that GRB10 is likely the causative gene of an overgrowth syndrome." (PMID 40577202, 2025).
phaeochromocytoma (1 paper, 2016). "All of the genes, but 2 (ITGA3 and GRB10), associated with the Wnt signaling pathway were upregulated in ZG versus ZF samples, irrespective of whether the comparison was made separately for ZG adjacent to an APA or a phaeochromocytoma." (PMID 27777363, 2016).
primary immunodeficiency (1 paper, 2024). "The high GRB10 subgroup was enriched in aminoacyl-tRNA biosynthesis, DNA replication, primary immunodeficiency, and mismatch repair, whereas the low GRB10 subgroup was enriched in sulfur metabolism." (PMID 39867577, 2024).
renal carcinoma (1 paper, 2016). A carcinoma arising from the epithelium of the renal parenchyma or the renal pelvis. "By contrast, GRB10 also acts as a tumor suppressor by negatively regulating phosphatidylinositol 3-kinase and insulin signaling, and is silenced in association with promoter methylation in renal cancer." (PMID 27977763, 2016).
sarcoma (1 paper, 2015). A usually aggressive malignant neoplasm of the soft tissue or bone. "Grb10 restoration also decreased proliferation in line 02.2, mirroring the previous effects observed in the sarcoma line 989 from our mouse model." (PMID 26000738, 2015). "Perhaps this is not surprising, given that most of the tumors from the irradiated Nf1+/- mice are sarcomas derived from muscle tissue, where Grb10 has a more prominent role than Grb14." (PMID 26000738, 2015). "To determine whether this effect in tumors was Nf1 dependent, we expressed Grb10 in the sarcoma line 963, which arose in a wildtype mouse and expresses neurofibromin protein." (PMID 26000738, 2015).
small cell lung carcinoma (1 paper, 2024). Small cell lung cancer (SCLC) is a highly aggressive malignant neoplasm, accounting for 10-15% of lung cancer cases, characterized byrapid growth, and early metastasis. "The immunohistochemical results confirmed that the expression level of GRB10 in adjacent tissues was significantly higher than that in human small cell lung cancer tissues." (PMID 39223679, 2024).
steatosis (1 paper, 2024). Increased lipid within the cytoplasm of cells. "A liver-specific Grb10 KO model was used to prove this expression was necessary for steatosis to occur." (PMID 38816743, 2024). "Given the evidence from mouse studies, involvement of GRB10 in steatosis and NAFLD merits further investigation." (PMID 38816743, 2024).
systemic sclerosis (1 paper, 2021). A chronic disorder, possibly autoimmune, marked by excessive production of collagen which results in hardening and thickening of body tissues. "GRB10 has been associated with a subtype of systemic sclerosis (lcSSc); patients with systemic sclerosis have higher expression of GRB10 in monocytes." (PMID 34294692, 2021).
vitamin B12 deficiency (1 paper, 2024). A disease characterized by low serum levels of vitamin B12, either inherited or acquired. "Overall, under combined vitamin B12 deficiency, the expression of Grb10 increased in maternal and fetal tissues (liver and brain) but not in maternal placenta in the F0 generation." (PMID 39543691, 2024). "The expression of hepatic Grb10 was elevated in fetal tissues among females in the BDFO and BDFD groups in the F1 generation, indicating that its levels were not impacted by vitamin B12 deficiency alone." (PMID 39543691, 2024).
tumor (30 papers, 2010 to 2025). "GRB10 is an adaptor protein associated with tyrosine kinase receptors and have been linked to increased tumor growth of different cancer types." (PMID 39450255, 2024). "The 867 tumor cell line, which was established from a tumor arising in an irradiated wildtype mouse and expresses Grb10 transcript levels similar to normal tissues, demonstrates loss of the paternal Grb10 allele." (PMID 26000738, 2015). "In tumors, Grb10 loss independently promotes Ras pathway hyperactivation, which promotes hyperproliferation, an early feature of tumor development." (PMID 26000738, 2015). "Our data indicates that Grb10-associated tumorigenesis is conditional on Grb10 loss cooperating with other tumor-promoting genetic events, as Grb10 silencing alone failed to confer anchorage independent growth to MEFs." (PMID 26000738, 2015). "The genetic factors responsible for OPG development in NF1 are not fully understood, however our experimental model provides a robust context in which to assess possible tumor promotion by loss of the imprinted paternal Grb10 allele." (PMID 26000738, 2015). "In human cancers, we found evidence for co-loss of neurofibromin and Grb10 expression in human glioblastoma, a tumor type in which NF1 is among the most significantly mutated genes." (PMID 26000738, 2015). "Human tumor sequencing databases reveal that the Grb10 and NF1 genes can be co-mutated in diverse tumor histologies." (PMID 26000738, 2015). "Because of the finding of GRB10 mutation in case #2, mutational analysis of GRB10 was also performed on tumor from case #3 (who also achieved a CR after IGF1R inhibitor therapy) and, remarkably, was also positive by Sanger sequencing." (PMID 25119929, 2014). "Two mutations were identified in her tumor sample collected between the two lines of treatment, a GRB10 Q107stop mutation and a PTPRD W775 stop mutation." (PMID 25119929, 2014). "We performed functional studies to test whether Grb10 restoration or loss alter fundamental features of the tumor growth." (PMID 26000738, 2015). "Together, these data indicate that Grb10 modulates Ras signaling in untransformed cells as well as tumor cells, and that loss of Grb10 in untransformed cells increases the magnitude and duration of Ras effector activation despite reduced insulin receptor levels." (PMID 26000738, 2015). "However, there are likely post-translational mechanisms mediating Grb10 loss, as among our tumor cell lines one tumor (the 867 tumor cell line) demonstrated Grb10 transcript levels comparable to normal control tissues but lacked detectable Grb10 protein." (PMID 26000738, 2015). "Indeed, our data suggest the presence of post-translational mechanisms mediating Grb10 loss, as among our tumor cell lines one tumor (the 867 tumor cell line) demonstrated Grb10 transcript levels comparable to normal control tissues but lacked detectable Grb10 protein." (PMID 26000738, 2015). "A comprehensive meta-analysis of published microarray data revealed that the abundance of GRB10 was decreased in many tumor types compared to that in normal tissue counterparts." (PMID 39223679, 2024). "(c) Synergistic action of APA and APA significantly stabilize the expression of GRB10 to play an anti-tumor effect." (PMID 39223679, 2024). "The results revealed that depleting the expression of GRB10 reduced the tumor size, tumor volume, and weight significantly." (PMID 35790975, 2022). "The knockdown of GRB10 was shown to inhibit cell proliferation, colony formation, and tumor formation in the xenograft models." (PMID 35790975, 2022).